ALG14 (ALG14 UDP-N-acetylglucosaminyltransferase subunit)
Description:
Part of the UDP-N-acetylglucosamine transferase complex that operates in the biosynthetic pathway of dolichol-linked oligosaccharides, the glycan precursors employed in protein asparagine (N)-glycosylation. The assembly of dolichol-linked oligosaccharides begins on the cytosolic side of the endoplasmic reticulum membrane and finishes in its lumen. The sequential addition of sugars to dolichol pyrophosphate produces dolichol-linked oligosaccharides containing fourteen sugars, including two GlcNAcs, nine mannoses and three glucoses. Once assembled, the oligosaccharides are transferred from the lipid to nascent proteins by oligosaccharyltransferases. Functions as a protein-membrane adapter recruiting ALG13 at the cytoplasmic face of the endoplasmic reticulum, where the complex catalyzes the second step of dolichol pyrophosphate biosynthesis, transferring a beta1,4-linked N-acetylglucosamine (GlcNAc) from UDP-GlcNAc to GlcNAc-pyrophosphatedolichol (Gn-PDol) to produce N,N'-diacetylchitobiosyl diphosphodolichol. N,N'-diacetylchitobiosyl diphosphodolichol is a substrate for ALG1, the following enzyme in the biosynthetic pathway.
Synonyms: MGC19780; CMS15; IDDEBF; MEPCA
Tractability: Antibody: UniProt predicts a signal peptide or a membrane-spanning region. PROTAC: ubiquitination databases record sites on it.
Gene: Protein-coding gene on chromosome 1 (94,974,405 to 95,072,951, reverse strand). Ensembl gene ENSG00000172339.
Subcellular location: Endoplasmic reticulum membrane
Subcellular location (Human Protein Atlas): Nucleoli; Nucleoplasm
Pathways (Reactome):
Disease: Defective ALG14 causes ALG14-CMS
Metabolism of proteins: Biosynthesis of the N-glycan precursor (dolichol lipid-linked oligosaccharide, LLO) and transfer to a nascent protein
Gene Ontology:
Molecular function: protein binding; protein-membrane adaptor activity
Biological process: dolichol-linked oligosaccharide biosynthetic process; protein N-linked glycosylation
Cellular component: cytoplasmic side of endoplasmic reticulum membrane; endoplasmic reticulum membrane; UDP-N-acetylglucosamine transferase complex
Genetic constraint (gnomAD): Loss-of-function variants: 17 observed, 24.17 expected, observed/expected ratio (o/e) 0.7, 90% interval 0.48 to 1.05. The upper end of that interval is the gene's LOEUF score, 1.05, which puts it in group 4 of 6, group 1 being the genes least tolerant of losing a copy. Missense variants: 288 observed, 288.93 expected, observed/expected ratio (o/e) 1, 90% interval 0.9 to 1.1. Synonymous variants: 89 observed, 109.08 expected, observed/expected ratio (o/e) 0.82, 90% interval 0.69 to 0.97.
Gene-disease validity (ClinGen):
ClinGen rates the evidence that ALG14 causes each of these diseases.
congenital disorder of glycosylation (autosomal recessive): Limited. Congenital disorder of glycosylation (CDG) is a fast growing group of inborn errors of metabolism characterized by defective activity of enzymes that participate in glycosylation (modification of proteins and other macromolecules by adding and processing of oligosaccharide side chains).
Homologues: Orthologues: chimpanzee ALG14 (98% identical), dog ALG14 (85% identical), pig ALG14 (81% identical), rat Alg14 (80% identical), mouse Alg14 (76% identical), tropical clawed frog alg14 (62% identical), zebrafish alg14 (57% identical), guinea pig ALG14 (54% identical), Drosophila melanogaster Alg14 (37% identical), Caenorhabditis elegans algn-14 (36% identical).
Diseases named in the same sentence as ALG14 in open-access papers:
ALG14 is named in the same sentence as 12 diseases in open-access papers, as found by Europe PMC text mining. Sharing a sentence is not in itself a finding about the gene and the disease. The quoted sentences say what the papers report.
congenital myasthenic syndrome (3 papers, 2019 to 2023). Congenital myasthenic syndrome (CMS) is a group of genetic disorders of impaired neuromuscular transmission at the motor endplate characterized by fatigable muscle weakness. "ALG13 variants underlie infantile-onset developmental and epileptic encephalopathy (DEE), while ALG14 gene mutants present as early lethal neurodegeneration with myasthenic and myopathic features, also known as congenital myasthenic syndrome (CMS)." (PMID 36200043, 2022).
arachnodactyly (1 paper, 2022). "Case 7 presented with generalized seizures, hearing loss, bilateral facial weakness, intellectual disability and arachnodactyly and Marfanoid appearance which is likely due to the combination of two deleterious variants in ALG14 leading to a complex multisystem disorder." (PMID 34908252, 2022).
breast carcinoma (1 paper, 2016). "We found two breast cancer-related lncRNAs, MALAT1 and XIST, were significantly and differentially co-expressed with mRNAs (ALG14, TOX4, and C12orf32) in tumor and normal breast tissue via trans-acting mechanism." (PMID 27597120, 2016).
Cerebral atrophy (1 paper, 2019). Atrophy (wasting, decrease in size of cells or tissue) affecting the cerebrum. "Mild cerebral atrophy was reported in SCN4A-related CMS and in ALG14-related CMS." (PMID 30808424, 2019).
epilepsy (1 paper, 2019). A brain disorder characterized by episodes of abnormally increased neuronal discharge resulting in transient episodes of sensory or motor neurological dysfunction, or psychic dysfunction. "Epilepsy was reported in patients with CMS due to SLC25A1 mutations, due to MUNC13–1 mutations, or due to ALG14 mutations." (PMID 30808424, 2019).
tumor (2 papers, 2016 to 2025). "By contrast, PQLC3 and ALG14 are primarily supported by bioinformatic associations or non-oncologic literature: PQLC3 has been identified in prognostic and tumor mutational burden-related gene sets, whereas ALG14 is a canonical component of N-linked glycosylation." (PMID 41403951, 2025).
cancer (1 paper, 2024). A tumor composed of atypical neoplastic, often pleomorphic cells that invade other tissues. "Targeting ALG14 or RFT1 led to HCC cell death in a consistent fashion, expanding a variety of cancer cell lines." (PMID 38927057, 2024).
infection (1 paper, 2013). The state of being infected such as from the introduction of a foreign agent such as serum, vaccine, antigenic substance or organism. "Conversion from incident to older infection status among these 7 algorithms occurred first for Alg3 (gp41 band ≤0.5), tightly followed by Alg3.1 (gp41≤1) and Alg5 (p24≤0.5), Alg6 (p17≤0.5), Alg14, Alg2 (gp120≤1) and finally Alg4 (p31 = 0)." (PMID 23990968, 2013).
neurological disorders (1 paper, 2022). "Pathogenic mutations in human ALG13 or ALG14 cause severe neurological disorders with a multisystem phenotype." (PMID 36200043, 2022). "In humans, mutations in ALG13 or ALG14 lead to severe neurological disorders with a multisystem phenotype, known as ALG13/14-CDG (congenital disorders of glycosylation)." (PMID 36200043, 2022).
ALG14 also shares sentences with these, for which no sentence is quoted: developmental and epileptic encephalopathy (1 paper); Intellectual disability (1); myopathy (1).